FOXP3 (forkhead box P3)
Diseases named in the same sentence as FOXP3 in open-access papers (continued):
Sharing a sentence is not in itself a finding about the gene and the disease.
oral cancer (6 papers, 2019 to 2025). "Among FOXP3 polymorphisms, rs3761548 (C>A) and rs2232365 (A>G), have been associated with cancer risk and immune escape in oral carcinoma." (PMID 40806346, 2025). "The carriers of the FOXP3 rs3761548 polymorphic variant “T” in male oral cancer patients who with alcohol consumption were associated with lower risk to develop greater tumor size and poorer cell differentiated grade." (PMID 37215447, 2023). "The betel quid chewers in male oral cancer patients who carried the FOXP3 rs3761548 polymorphic variant “T” were significantly associated with lower risk to develop oral cancer and moderate or poorer cell differentiated grade." (PMID 37215447, 2023). "The betel quid chewers with genotypic variant “T” of FOXP3 rs3761548 in male oral cancer patients were associated with lower risk of cell differentiated grade [AOR (95% CI) = 0.592 (0.377-0.930); p = 0.023]." (PMID 37215447, 2023). "The highest distribution frequencies in patients with oral cancer of FOXP3 genetic polymorphisms rs3761547, rs3761548, rs3761549, and rs2232365 were polymorphic variant T, polymorphic variant G, polymorphic variant G, and polymorphic variant T, respectively." (PMID 37215447, 2023). "In this study, we focused on the correlations of FOXP3 single-nucleotide polymorphisms (SNPs) to oral cancer susceptibility and clinicopathological characteristics." (PMID 37215447, 2023). "In this study, we focused on four SNPs of FOXP3 rs3761547, rs3761548, rs3761549, and rs2232365, and try to elucidate their associations to oral cancer susceptibility and clinicopathological characteristics with environmental risk factors." (PMID 37215447, 2023). "We further analyzed the ORs and 95% CIs of oral cancer associated with FOXP3 genotypic frequencies among betel quid chewer." (PMID 37215447, 2023). "In conclusion, our results have revealed that the FOXP3 rs3761548 polymorphic variant “T” was associated with lower risk of oral cancer susceptibility, greater tumor size, and cell differentiated grade among betel quid chewers." (PMID 37215447, 2023). "In our study, no statistical significant associations were found between the oral cancer patients and the controls, suggesting a limited carcinogenic effect and disease susceptibility of FOXP3 polymorphisms to oral cancer." (PMID 37215447, 2023). "The results showed that the betel quid chewer who carried the FOXP3 rs3761548 polymorphic variant “T” were significantly associated with lower risk to develop oral cancer [AOR (95% CI) = 0.649 (0.437-0.964); p = 0.032]." (PMID 37215447, 2023). "In conclusion, our study first demonstrated the associations of FOXP3 polymorphisms to oral cancer disease susceptibility and clinical statuses." (PMID 37215447, 2023). "We further examined the influence of the FOXP3 genotypic frequencies to oral cancer susceptibility." (PMID 37215447, 2023). "In this study, we revealed the associations between the FOXP3 SNPs and oral cancer." (PMID 37215447, 2023). "In 142 of total 856 patients, a significant association was found in those individuals who carried the FOXP3 rs3761548 polymorphic variant T, with a lower risk of oral cancer susceptibility [The adjusted odds ratio (AOR) (95% CI):0.649 (0.437-0.964); p = 0.032]." (PMID 37215447, 2023). "The FOXP3 rs3761548 may play a role as pivotal tumor marker to predict and evaluate oral cancer disease susceptibility, tumor progression, and prognosis." (PMID 37215447, 2023). "The FOXP3 rs3761548 polymorphisms may play a role as pivotal biomarkers to predict oral cancer disease development and prognosis." (PMID 37215447, 2023). "The FOXP3 SNPs rs3761547, rs3761548, rs3761549, and rs2232365 in 1053 controls and 1175 male patients with oral cancer were analyzed with real-time polymerase chain reaction." (PMID 37215447, 2023). "Further functional studies investigating what effects oral CAFs activated through oral cancer-derived EVs have on CD25+FOXP3+ T cells would hence be highly interesting." (PMID 37745296, 2023).
oral cancer (continued). "Increased CCL22 mRNA levels are correlated with increased FoxP3 mRNA levels in oral cancer specimens." (PMID 31842422, 2019). "This indicates that the decreased levels of FOXP3 expression observed postoperatively in oral cancer patients compared to controls with minor surgery in the current study might also be an expression of impaired immune responsiveness." (PMID 37568571, 2023). "The limitations to our study is that we lack of the data of FOXP3 expression levels and the exact cellular localization of FOXP3 to these oral cancer patients, so more detailed analysis could not be performed." (PMID 37215447, 2023).
osteoporosis (6 papers, 2018 to 2024). A condition of reduced bone mass, with decreased cortical thickness and a decrease in the number and size of the trabeculae of cancellous bone (but normal chemical composition), resulting in increased fracture incidence. "FOXP3, a transcription factor for Treg cells, was elevated after IL-33 treatment, which was otherwise low in the D-gal–administered group and Tregs have been shown to reduce bone loss and osteoporosis." (PMID 39224568, 2024). "Furthermore, IL-17+/FOXP3+ percentage analysis indicated that intestinal Th17/Treg imbalance occurred in estrogen deficiency-induced osteoporosis, and LGG treatment significantly downregulated this percentage, having a significant effect on intestinal inflammation." (PMID 36941563, 2023). "Compared with mice in the Con group, there were significantly decreased contents of BGP, Ca2+, CT, E2, FOXP3, and HyP in the serum of the Mod group (p < .05), indicating the osteoporosis models were successfully and efficiently established in the research." (PMID 37324858, 2023). "In osteoporosis-related alveolar bone resorption, IL-6—an osteoclastogenesis-promoting cytokine—promotes the conversion of forkhead box P3 (FoxP3) T cells to T helper 17 (Th17) cells, which guard against germs but induce osteoclast formation and thus, bone injury." (PMID 37569338, 2023). "Were CD4+CD25+Foxp3+ Tregs involved in the development of osteoporosis?" (PMID 30406140, 2018). "The osteoporosis was significantly improved in the SG group compared with the OVX group, and the diversity of intestinal flora, the secretion level of SCFAs and the expression level of FOXP3 were significantly increased compared with the OVX group." (PMID 38525084, 2024). "These may indicate that the Shengu granules may have increased FOXP3 expression regulating treg conversion and increased SCFA regulating Th17 conversion, thus ameliorating the effect of the Th17/treg axis on osteoporosis." (PMID 38525084, 2024).
pancreatitis (6 papers, 2013 to 2025). Inflammation of the pancreas. "Foxp3 immunostaining of the pancreas showed an abundant infiltration of Foxp3-positive cells in 10-week-old MRL/Mp mice at the early stage of the pancreatitis." (PMID 23781248, 2013). "MRL/Mp mice treated with poly I:C showed early development of pancreatitis with abundant infiltration of Foxp3-positive cells." (PMID 23781248, 2013). "During Pancreatitis increased levels of FOXP3+/CD25+ regulatory T cells (Tregs) could be detected in mouse models as well as in patients in a severity dependent manner." (PMID 40560328, 2025). "We observed a steady increase in the expression of FOXP3, LRRC32, as well as FOSL2 and IL6 from normal through pancreatitis to PAAD." (PMID 36932385, 2023).
Papillary Thyroid Cancer (6 papers, 2016 to 2025). "In contrast, French and collaborators demonstrated that the presence of regulatory T lymphocytes (CD4+ FoxP3+) was greater in metastatic lymph nodes and was related to the aggressiveness of papillary carcinoma." (PMID 38913547, 2024).
rhinitis (6 papers, 2013 to 2020). An inflammation of the mucous membrane lining the nose, usually associated with nasal discharge. "This indicated that LA may alleviate rhinitis through suppressing the expression of Th2 cytokines via improving Treg Foxp3 production." (PMID 32719431, 2020). "One study reported stronger associations between polycyclic aromatic hydrocarbon (PAH) exposure and forkhead box P3 (FOXP3) methylation among nonasthmatic rhinitis children, compared to those among non-atopic or asthmatic children with/without rhinitis." (PMID 28588744, 2017).
sarcoma (6 papers, 2013 to 2025). A usually aggressive malignant neoplasm of the soft tissue or bone. "The whole TCGA sarcoma cohort was next explored regarding immune regulatory Foxp3+ cells." (PMID 33803245, 2021). "In fact, sarcomas induced by MCA increase the frequency of Treg (FoxP3+ of CD3+, CD4+ cells, Sup." (PMID 26076008, 2015). "Treg infiltration varies across sarcoma subtypes, with GIST showing the highest density of FOXP3+ density (36%) among sarcomas." (PMID 40469285, 2025). "High-grade sarcoma, such as leiomyosarcoma, exhibits higher infiltration of CD3+, CD8+, and FOXP3+ T-cells, while infiltrating CD20+ B-cells, though rarely detected in STS, are correlated to improved outcomes." (PMID 40469285, 2025). "This study aimed to investigate the level of CD4+ T cells and forkhead box protein P3+ (FoxP3+) Treg cells, as well as T-cell-related-cytokines such as TNF-α, IFN-γ, IL-17A, and TGF-β1 in the peripheral blood of sarcoma patients." (PMID 36005179, 2022). "In examining the status of regulatory cells, we have observed no significant changes in CD4+CD25+Foxp3+ T regulatory cells in various immune compartments in day 21 NLGP-treated sarcoma bearing mice (data not shown)." (PMID 23326300, 2013). "Transcriptomics performed in the TCGA sarcoma cohort confirmed the prognostic value of combining CD11c with CD8 (259 patients, p = 0.005), irrespective of FOXP3 levels and in a CD274 (PD-LI)-rich tumor microenvironment." (PMID 33803245, 2021).
skin tumors (6 papers, 2007 to 2021). "Foxp3 mRNA levels were significantly elevated in skin tumors, while IL-10 mRNA levels were significantly elevated in skin tumors, draining lymph nodes, and lung metastatic nodules in CCL17 TG mice." (PMID 33670758, 2021). "This study demonstrates that patients who have previously developed a cSCC have increased numbers of FOXP3+ CD4+ T cells, which may prove to be a useful marker of skin cancer in transplant recipients." (PMID 25250867, 2014).
uveal melanoma (6 papers, 2012 to 2022). A melanoma derived from melanocytes of the uveal tract. "The results showed that the mRNA level of Foxp3 was higher in uveal melanoma cells than that of ARPE-19 cells." (PMID 36466923, 2022). "Forkhead box protein P3 (FOXP3) positive TReg cells have been described in up to 24% of primary uveal melanoma tumors." (PMID 33317028, 2020). "Consistently, the protein levels of FOXP3 were significantly increased in uveal melanoma cells." (PMID 36466923, 2022). "FOXP3, a marker of TReg cells has been demonstrated in uveal melanoma liver metastasis." (PMID 33317028, 2020). "Two studies recently evaluated FoxP3 expression on T cells infiltrating primary uveal melanomas." (PMID 23060881, 2012). "However, the presence of FOXP3+ Treg in cycloxygenase-2 (COX-2) positive tumors did predict poor survival of uveal melanoma patients." (PMID 23060881, 2012). "First, we examined the mRNA expression levels of Foxp3 in ARPE-19 cells and uveal melanoma cells, including MUM2B and OCM-1A cells." (PMID 36466923, 2022).
visceral leishmaniasis (6 papers, 2012 to 2020). A severe form of leishmaniasis characterized by irregular bouts of fever, substantial weight loss, swelling of the spleen and liver, and anemia (which may be serious). "In visceral leishmaniasis, Foxp3− T cells were found to be the predominant IL-10 producers in the spleen." (PMID 23555256, 2013). "The lack of correlation between FoxP3+ and IL-10+ cells suggests that other regulatory cells could be the source of IL-10, since it has been described that IL-10-producing CD25− Foxp3− T cells are involved in the pathogenesis of visceral leishmaniasis." (PMID 29743809, 2018). "Additionally the data presented herein suggests that splenic FoxP3- and IL-17-producing cells are involved in the chronicity of visceral leishmaniasis." (PMID 25200768, 2014). "In India, spleen aspiration and peripheral blood of patients with visceral leishmaniasis and healthy people who were living in endemic area were investigated and observed no increasing in Foxp3 in patients." (PMID 31543906, 2019). "In the last decade when the number of visceral leishmaniasis in immunocompromised patients has been increasing, our data presented herein offered a novel insight into the possibly involvement of CD4+Foxp3+ Tregs in persistent L. donovani infection in the liver of immunodeficient hosts." (PMID 22928057, 2012). "In comparison with the spleens of the other two patients without visceral leishmaniasis, an increase was observed in the CD4/CD8 ratio and in the number of IL-10- and FoxP3-producing cells, while the number of IL-17-producing cells was lower in the spleen of the patient with visceral leishmaniasis." (PMID 25200768, 2014).
acute kidney injury (5 papers, 2014 to 2022). Sudden and sustained deterioration of the kidney function characterized by decreased glomerular filtration rate, increased serum creatinine or oliguria. "Membranous nephropathy leading to renal failure completed in both cases the clinical phenotypes that should be included in the clinical panorama of FOXP3 failure." (PMID 35479070, 2022). "In a similar way, transfer of Foxp3-transduced T cells reduced proteinuria and renal glomerulosclerosis in rats treated with Adriamycin, a murine model of chronic proteinuria leading to renal failure." (PMID 25343479, 2014). "We attempted to study peripherally circulating T-cells expressing RORγt+Foxp3+ dynamics in acute kidney injury (AKI) and chronic kidney disease (CKD)." (PMID 34868786, 2021). "Ex vivo expansion and transfer modificated Foxp3-transduced Tregs or in vivo-induced Tregs can protect against ischemia acute kidney injury (AKI) and decrease infiltration of inflammatory cells and proteinuria in CKD animal models." (PMID 29619880, 2018).
acute lymphoblastic leukemia (5 papers, 2019 to 2024). Leukemia with an acute onset, characterized by the presence of lymphoblasts in the bone marrow and the peripheral blood. "The role of CD4+CD25+FOXP3+ regulatory T cells (Tregs) in acute lymphoblastic leukemia development has been linked to a higher immunosuppressive activity compared to the Tregs of healthy subjects, leading to the inhibition of anti-tumor immunity." (PMID 37569699, 2023). "Exosomes extracted from patients with acute lymphoblastic leukemia (ALL) induced apoptosis in T lymphocytes and modulated the T‐cell profile to become Treg through the upregulation of FOXP3, IL‐10 and TGF‐β." (PMID 39611045, 2024). "First, in patients with chronic lymphocytic leukemia (CLL), AML, or adult acute lymphoblastic leukemia (ALL), TIGIT is commonly upregulated on CD4+ T cells, CD8+ T cells, Foxp3 + γδ T cells, or NK cells compared with healthy individuals." (PMID 37291608, 2023). "This work was planned to investigate the impact of FOXP3 (rs3761548C/A and rs3761549C/T) and ROR-γ (rs9017A/G & rs9826A/G) gene polymorphism on the vulnerability of pediatric Egyptians to acute lymphoblastic leukemia (ALL)." (PMID 36083385, 2022).
acute respiratory distress syndrome (5 papers, 2019 to 2026). Progressive and life-threatening pulmonary distress in the absence of an underlying pulmonary condition, usually following major trauma or surgery. "TIM-1+ B cells were also determined to promote Foxp3 expression in CD4+ T cells in acute respiratory distress syndrome." (PMID 30917149, 2019). "FOXP3+ natural regulatory T cells (nTregs) promote resolution of inflammation and repair of epithelial damage following viral pneumonia–induced lung injury, thus representing a cellular therapy for patients with severe viral pneumonia and the acute respiratory distress syndrome." (PMID 40956625, 2025). "In studies of acute respiratory distress syndrome (ARDS), IL-33 has been shown to play a critical role in modulating post-injury inflammation by controlling local cytokine levels and populations of Foxp3+ Tregs." (PMID 39301028, 2024). "The eCB, AEA mitigated Staphylococcal enterotoxin B (SEB)-induced acute respiratory distress syndrome (ARDS) in mice via down-regulation of miRNA-23a-3p, which up-regulated arginase and TGF-β2, and miRNA-34a-5p that prompted FoxP3 induction." (PMID 36776218, 2022).
airway allergy (5 papers, 2012 to 2017). "Using multigene reporter and fate-reporter systems, we demonstrate that a significant proportion of Th2 cells derive from Foxp3+ cells after Heligmosomoides polygyrus infection and airway allergy." (PMID 28507062, 2017). "Fate reporter and adoptive transfer strategies identified that a significant proportion of Th2 cells originated from Foxp3-expressing cells after H. polygyrus infection or house dust mite (HDM)–induced airway allergy." (PMID 28507062, 2017). "It has been verified that Foxp3+Treg quantity and/or function decrease in the peripheral blood of patients with respiratory allergy, and recover after immunotherapy." (PMID 24460842, 2014). "Excretory/secretory products of H. polygyrus induced Foxp3 expression in T cells in vitro through the TGF-β pathway and are able to suppress airway allergy." (PMID 23844022, 2013). "To determine whether the development of ex-Foxp3 Th2 cells was restricted to antihelminth immune responses in the intestine, we measured the frequency of ex-Foxp3 Th2 cells in the lung and local draining mediastinal LN after HDM-induced airway allergy." (PMID 28507062, 2017). "In this paper we aimed to test how ASIT influences the frequency of FoxP3 Tregs in allergic children and whether FoxP3 Tregs number differs in patients with various clinical manifestations of the disease (respiratory allergy with or without concomitant FA and/or AD)." (PMID 26457309, 2015).
allergic conjunctivitis (5 papers, 2013 to 2025). "microRNA146a was also reported to suppress exacerbation of inflammation in allergic conjunctivitis by upregulation of FOXP3 and downregulation of pSTAT3 thus demonstrating a protective mechanism." (PMID 38983073, 2023). "We explore the possibility of inducing Treg CD4+CD25+FOXP3+ cells from the PBMC of patients with allergic conjunctivitis after specific allergen stimulation." (PMID 33114004, 2020).
amyotrophic lateral sclerosis (5 papers, 2020 to 2024). Amyotrophic lateral sclerosis (ALS) is a neurodegenerative disease characterized by progressive muscular paralysis reflecting degeneration of motor neurons in the primary motor cortex, corticospinal tracts, brainstem and spinal cord. "We have shown that Tregs from patients with amyotrophic lateral sclerosis (ALS) have reduced expression of full-length (FL) FoxP3, while other truncated splice variants are expressed predominantly." (PMID 38790984, 2024). "Crucial to the neuroinflammatory modulation, T regulatory cells (Tregs), a subset of T cells characterized by expression of CD4+, FoxP3+, CD25+, are known as potential modifiers of disease progression in Amyotrophic Lateral Sclerosis (ALS)." (PMID 39845951, 2024). "In amyotrophic lateral sclerosis (ALS), Tregs have protective effects that can delay the disease progression, and early reduction of Foxp3 levels can be used to screen patients with rapid progression." (PMID 33551792, 2020). "The safety and potential efficacy of allogeneic cord-blood-derived FOXP3+ Treg cells are also being evaluated in an ongoing clinical trial involving six patients with amyotrophic lateral sclerosis (ALS) without HLA matching (NCT05695521)." (PMID 39697333, 2024).